PRL (prolactin)
Diseases named in the same sentence as PRL in open-access papers (continued):
Sharing a sentence is not in itself a finding about the gene and the disease.
Infertility (continued). "Altered prolactin secretion in infertile patients with endometriosis was accompanied by luteal insufficiency, which was more frequent in infertile patients with endometriosis (78.9%) than in fertile patients with endometriosis (42.9%) or fertile women without endometriosis (0%)." (PMID 39407928, 2024). "Novel strategies in the treatment of endometriosis-related infertility, based on its connection with prolactin such as the use of prolactin receptor antibodies and prolactin receptor antagonists, are under investigation, but adequate clinical studies have yet to be undertaken." (PMID 39407928, 2024). "The authors concluded that “alteration in PRL dynamics may contribute to infertility in women with endometriosis and may be a part of the pathophysiology of this disease’’." (PMID 39407928, 2024). "In females, high prolactin levels or a lack of hypothalamic prolactin receptors can cause infertility." (PMID 39304061, 2024). "The authors of the study concluded that decreased serum oestradiol levels and altered PRL secretion after TRH administration in infertile patients with minimal/mild endometriosis were related to ovulatory dysfunction and infertility in this group of patients without tubal occlusion." (PMID 39407928, 2024). "Previous studies have shown that serum high PRL concentration could contribute to infertility by inducing oxidative damage." (PMID 37833858, 2023). "Symptoms secondary to high prolactin levels in premenopausal women may include hypogonadism and hypoestrogenism with infertility, galactorrhea, low libido, vaginal dryness, dyspareunia, and low bone density." (PMID 36835974, 2023). "Increased prolactin levels inhibit the pulsatile secretion of gonadotropin-releasing hormones by interfering with hypothalamic kisspeptin-secreting cells, resulting in menstrual cycle dysfunction, including oligomenorrhea or amenorrhea, and infertility." (PMID 36835974, 2023). "Because PRL is essential for maintaining luteal function and progesterone secretion, PRL deficiency caused by MARK2 dysfunction may lead to infertility in females." (PMID 37901230, 2023). "Shift-induced circadian rhythm disorders affect reproductive health through the deregulation of sex steroid, gonadotropin, and prolactin production, which may result in infertility and abnormalities in the menstrual cycles of women working shifts." (PMID 35805742, 2022). "However, infertile PCOS womenmainly showed orgasm dysfunction as a result of lowerlevels of prolactin, and lower total FSFI and arousal as aresult of marital duration." (PMID 33497050, 2021). "This study was conducted with 182 infertile women with Hyper-PRL." (PMID 35098010, 2021). "Hyper-PRL is one of the most frequent etiologies of infertility in women." (PMID 35098010, 2021). "It has also been documented that serum prolactin levels are significantly elevated in women with endometriosis, however, the examinations were mainly focused on patients with endometriosis and accompanying infertility." (PMID 33669013, 2021). "Nonetheless, the function of beta-cells and status of metabolism remain unknown in infertile patients with PCOS exhibiting normal serum PRL levels." (PMID 33716958, 2021). "It is important for infertility to maintain low PRL levels from 10-12 months." (PMID 33426414, 2020). "However, studies relating sperm motility with serum levels ofPRL reported decreased or higher levels of the hormone in the individuals with asthenozoospermia but the excessive level of serum PRL was correlated with infertility, impotence andhypogonadism." (PMID 32405170, 2020). "Therefore, we concluded that the low PRL in infertile PCOS patients is an effective marker of poor metabolic spectrum and higher cardiovascular risk." (PMID 32477263, 2020). "Increased PRL levels have been implicated in the endometriosis-induced infertility, but studies have failed to prove a clear causal relationship between PRL levels and endometriosis, as discordant results have been reported." (PMID 33162942, 2020).
Infertility (continued). "The results obtained and the correlations confirmed concerning cortisol and prolactin as predictive factors for the achievement of pregnancy would provide women treated for infertility with better diagnostics due to the prospective characteristics and easy measurement of specific parameters." (PMID 33081268, 2020). "Altogether, these findings lead to the conclusion that PRL appear to be a useful biomarker of endometriosis-related infertility and that dopamine agonists might be successfully administered to target endometriotic lesions." (PMID 33162942, 2020). "Knock-out PRL-R male mice have infertility proposing a role of PRL in spermatogenesis." (PMID 31847209, 2019). "The relationship between endometrial histology and clinical parameters such as including luteinizing hormone, follicle-stimulating hormone, thyroid-stimulating hormone, testosterone, prolactin, fasting blood sugar, body mass index (BMI), and infertility duration was analyzed." (PMID 32043069, 2019). "WC had a negative association with prolactin in both primary (R = − 0.236) and secondary (R = − 0.232) infertility." (PMID 31455408, 2019). "There is controversy asto whether abnormal prolactin secretion is directly involved in infertility inpatients with endometriosis (Gardner etal., 2017; Esmaeilzadehet al., 2015)." (PMID 30969738, 2019). "The unique finding of this study was that prolactin levels of women with tubal factors as the cause of infertility showed negative association with central adiposity indices (WC and WHtR)." (PMID 31455408, 2019). "Also, WS root extract was found to decrease prolactin level after 3 months of administration among infertile men." (PMID 29670898, 2018). "The dosage of progesterone and prolactin on day 09 afterfollicular retrieval could function as a predictive marker of success infertility treatments." (PMID 29542885, 2018). "The levels of sex hormones such as LH, FSH, prolactin, testosterone in the infertile men were markedly higher than those in the healthy men, and the frequency of hormonal changes in the azoospermic men was higher than that in other subgroups of the infertile men." (PMID 29404532, 2017). "Therefore, treatment with drugs that lowered prolactin levels resulted in pregnancy for 24% of the infertile women." (PMID 29387827, 2017). "Among other aspects, we will discuss whether the interaction between prolactin and the Kiss1-expressing neurons can affect reproduction and how kisspeptins may become a novel therapeutic approach to treat prolactin-induced infertility." (PMID 27901187, 2016). "Nevertheless, whether kisspeptin may be used as a novel therapeutic approach to treat prolactin-induced infertility in humans still requires further investigation." (PMID 27901187, 2016). "The objective of the present review is to summarize and discuss recent advances in the discovery of possible mechanisms linking prolactin signaling and the control of reproduction, especially regarding the role of kisspeptins as novel potential targets to treat prolactin-induced infertility." (PMID 27901187, 2016). "Prolactin (PRL)-secreting tumors are the most common of all functional pituitary tumors and cause amenorrhea, infertility, and galactorrhea in females, and impotence or infertility in males." (PMID 26733942, 2015). "However, more studies aimed at identifying the role of PRL in infertile women with endometriosis are required." (PMID 26000006, 2015). "Polycystic ovaries with high levels of prolactin tend to lead to infertility problems." (PMID 22363892, 2011). "It seems that the increase in prolactin serum concentrations does not cause deleterious effects on the outcome from infertility treatment." (PMID 16444392, 2005). "Additionally, exploring the potential molecular interactions between iron metabolism and prolactin regulation could provide valuable insights into the pathophysiology of infertility." (PMID 40535391, 2025).
Infertility (continued). "Moreover, the role of prolactin dysregulation following seizures, as well as the impact of temporal lobe epilepsy on gonadotropin-releasing hormone (GnRH) pulsatility, is examined in relation to infertility outcomes." (PMID 41323226, 2025). "The observed disruption of lactational infertility in Prlrlox/lox/Kiss1Cre mice is particularly remarkable given that Prlr deletion is restricted to arcuate kisspeptin neurons in this model, and prolactin action on RP3V kisspeptin neurons and on gonadotrophs in the pituitary gland are unaffected." (PMID 39819370, 2025). "However, the selection of an antipsychotic that does not raise prolactin levels can prevent this cause of infertility." (PMID 41008479, 2025). "However, TTST, E2, and PRL had comparable levels between fertile and infertile men." (PMID 40425698, 2025). "However, few studies show the association between high prolactin levels and anemia but not in infertile women." (PMID 40535391, 2025). "Although Zmiz1d/d ovulated in response to exogenous gonadotrophins, fewer oocytes were released, and although serum prolactin levels were comparable, serum progesterone levels of 3.5 dpc Zmiz1d/d were reduced, indicating that ovarian dysfunction contributed to the infertility." (PMID 41321316, 2025). "Extrapituitary or peripheral prolactin has similar chemical, biological, and immunological properties as pituitary prolactin, suggesting the possible role of peripheral prolactin in the development of subfertility and infertility, but the exact mechanisms are not fully understood." (PMID 39407928, 2024). "An excellent study including 55 women with endometriosis-related infertility was performed more than 30 years ago and showed that nocturnal prolactin secretion may be altered in infertile women with endometriosis, with an exaggerated and prolonged nocturnal peak." (PMID 39407928, 2024). "There is also the possibility of the existence of some unknown factor or disrupted signalling pathway that could interfere with pituitary prolactin secretion or local prolactin action, which is at the same time responsible for subfertility or infertility in some patients with endometriosis." (PMID 39407928, 2024). "The authors concluded that high prolactin serum levels contributed to the subfertility in endometriotic patients and hypothesised that stress, which increases the prolactin levels, might be involved in the progression of disease and the development of endometriosis-induced infertility." (PMID 39407928, 2024). "Moreover, they proposed that serum PRL levels in infertile women with PCOS might be a predictor for IR and ß-cell dysfunction." (PMID 38004264, 2023). "Besides, clinical observations in hypoprolactinemic infertile men have shown that the restoration of normal PRL levels leads to an increase in sperm density and quality and restores fertility, suggesting a role for PRL in regulating the testis and accessory glands." (PMID 37954671, 2023). "Moreover, the mechanisms by which prolactin may exert its role in fertility and infertility were summarized." (PMID 36678618, 2023). "Studies have shown normalization of prolactin levels in approximately 70–80% of patients; tumor size reduction was documented in about 60% of patients, with the resolution of galactorrhea, amenorrhea, infertility, and sexual function in more than half of patients." (PMID 36835974, 2023). "Elevated concentrations of prolactin may bring about infertility in mammals since prolactin inhibits the secretion of luteinising hormone and follicle stimulating hormone and consequently brings about a form of natural suppression of reproduction usually arising during lactation." (PMID 36359164, 2022). "Our clinical study lend support to the assumption that serum PRL levels within the normal range associates with glucose metabolism changes in infertile women with PCOS, suggesting that PRL may be a sensitive marker to predict insulin resistance and dysfunction of beta-cells." (PMID 33716958, 2021).
Infertility (continued). "Thus, we propose that serum PRL levels in infertile women with PCOS may be a predictor for insulin resistance and a functional deficiency of beta-cells." (PMID 33716958, 2021). "Also, studies have shown that excessive secretion of prolactin reduces the pulsatile release of GnRH and impairs normal gonadal steroid secretion, which leads to positive feedback effects at the pituitary and hypothalamic levels, and ultimately infertility." (PMID 35098010, 2021). "Assessment is recommended of the levels of cortisol and prolactin due to their effect on the levels of estradiol and progesterone and endothelial thickness after ovulation, which is directly related to the possibility of becoming pregnant during infertility treatment." (PMID 33081268, 2020). "However, among serum hormones in different subtypes of infertility, only PRL showed thesignificant prediction of Normozoospermia (AUC=0.836, Z=4.916, p<0.001) at a cut off value of >119.04 μIU/ml with 92.86% sensitivity (95% CI=66.1-98.8) and 65.00% specificity(95% CI=54.8-74.3)." (PMID 32405170, 2020). "Moreover, acupuncture may be a useful intervention to reduce infertility-related stress and depression by changing the stress hormones (serum cortisol and prolactin)." (PMID 31200701, 2019). "Additionally, if our speculation is right, one would expect that knock–in of hPRL expression from the extrapituitary promoter alone would be sufficient to rescue PRL−/− mice from infertility." (PMID 16998840, 2006). "Another study has also shown that prolactin correlated negatively with HOMA-IR and HOMA-B in infertile women with PCOS." (PMID 40362476, 2025). "Increased serum prolactin (PRL) levels are a common finding when investigating patients with complaints of menstrual irregularity and infertility." (PMID 38765533, 2024). "This systematic review and meta-analysis aimed to summarise the strength of the correlation between serum PRL and thyroid stimulating hormone (TSH) in infertile women and to explore selected factors influencing the correlation." (PMID 38456102, 2024). "Our results highlighted a significant positive moderate correlation between serum PRL and serum TSH in infertile women." (PMID 38456102, 2024). "The original research paper describing the correlation between PRL and TSH in reproductive-age women with infertility (primary and secondary) was included." (PMID 38456102, 2024). "Consistent with previous reports, marked distinctions were identified between the no‐PCOS and PCOS groups concerning variables such as age, BMI, AMH, AFC, infertile duration, FSH, LH, FSH/LH ratio, PRL, and T, as well as TG, TC, HDL, and LDL." (PMID 39139929, 2024). "While serum AMH ≤ 4, primary infertility, serum prolactin ≤ 20 (ng/mL), baseline LH/FSH < 1.5, and infertility duration < 4 years were correlated with a higher prediction of clinical pregnancy in the CC-Placebo group." (PMID 39202581, 2024). "In the CC-Placebo group, there was a greater prediction of clinical pregnancy for those with serum AMH (<4), primary infertility, serum prolactin ≤ 20 (ng/mL), baseline LH/FSH < 1.5, and infertility duration < 4 years." (PMID 39202581, 2024). "These parameters include age, obesity and BMI, etiology of infertility, duration of infertility, and serum hormonal levels FSH, LH total testosterone (tT), prolactin (PRL), and inhibin B." (PMID 39767586, 2024). "Infertility treatment in patients with HPRL is also carried out with DA, aiming to normalize prolactin (PRL) levels." (PMID 38765515, 2024). "Thus, it was shown that infertile women might have a different personality profile in comparison with fertile women, characterized by more suspicion, guilt and hostility, accompanied by increased stress hormone levels such as prolactin and cortisol." (PMID 36678618, 2023). "Prolactin (PRL) serves as a biomarker for the exclusion of HPRL, which can manifest with oligomenorrhea, amenorrhea, infertility, and mild hirsutism." (PMID 38004264, 2023).
Infertility (continued). "Curcumin nanomicelle improved semen parameters and testosterone levels, reduced FSH, LH, and prolactin, and improved oxidative stress through the reduction of serum MDA, CRP, and TNF and by increasing the serum total antioxidant capacity in infertile males." (PMID 34829704, 2021). "According to their HCG test result, we compared the patients in terms of age, BMI, infertility duration, number of cycles, FSH, LH, E2, P, TSH, and PRL." (PMID 32759097, 2021). "In differentsubgroups of infertile males, mean (±SD) levels of LH, FSH, and PRL in azoospermia and oligozoospermia were 11.77±10.28, 16.82±17.27, 197.55±83.09 and 7.64±3.21,9.95±13.94, 215.48±82.03, respectively." (PMID 32405170, 2020). "Hence, we’d think that more PRL may lead to hypogonadism and infertility in females." (PMID 32727366, 2020). "So, LH, FSH, and PRL levelswere found elevated significantly in azoospermic, oligozoospermic and asthenozoospermic infertile males while normozoospermic males had significantly higher levels of FSH and PRL incompared to fertile controls." (PMID 32405170, 2020). "This study aimed to analyze the serum PRL level in a large number of infertile PCOS patients and its correlation with various types of metabolic indicators to better understand the relationship between PRL and metabolism." (PMID 32477263, 2020). "Age, number of years of infertility, BMI, basic FSH, basic LH, basic E2, basic PRL, basic T, basic progesterone (P), AMH, intimal thickness, number of oocytes harvested, and total Gn dosage of pregnant and non-pregnant patients were compared." (PMID 33343511, 2020). "We studied the interactions between the two menstrual cycle hormones i.e., cortisol (COR) and prolactin (PRL), along with the ultrasonographic ovulation parameters in a group of N = 205 women with diagnosed infertility." (PMID 33081268, 2020). "Accordingly, we found statistically significant differences in infertility duration, progressive motility rate, sperm volume, sperm motility, FSH, T, and PRL (P<0.05)." (PMID 28515223, 2017). "Baseline infertility investigations, including hormonal assessments for TSH and prolactin, pelvic ultrasonography, and semen analysis, were unremarkable." (PMID 28603472, 2017). "The hormonal status of women treated for infertility during the pandemic significantly changed due to a decrease in FSH (follicle-stimulating hormone) and LH (luteinizing hormone) secretion and an increase in PRL (prolactin)." (PMID 39941391, 2025). "A recent study has documented lower levels of prolactin and a negative correlation between prolactin and insulin resistance in infertile women with PCOS." (PMID 40362476, 2025). "Prolactinomas produce excess prolactin with symptoms of galactorrhea (milk discharge from breasts), amenorrhea (absence of menstrual periods), infertility, and sexual dysfunction (Singh)." (PMID 40144450, 2025). "Thus, lactotroph tumors (30–50% of all PitNET) secrete high levels of prolactin (PRL), leading to amenorrhea–galactorrhea syndrome in females and impotence in males, with infertility." (PMID 40362297, 2025). "Metyrapone preserved fertility despite low prolactin, whereas metyrosine failed to prevent infertility despite normalizing prolactin levels." (PMID 41304935, 2025). "Additionally, elevated levels of DHEAS, testosterone, insulin, prolactin, triglycerides, TG/HDL, AIP, and LCI in the infertile cohort underscore the multifactorial nature of infertility in PCOS." (PMID 40802395, 2025). "After adjusting for BMI and age, our results showed that serum prolactin ≤ 20 (ng/mL), serum AMH ≤ 4, secondary infertility, infertility duration < 4 years, and baseline LH/FSH < 1.5 were correlated with a higher prediction of clinical pregnancy in the CC-HCG group." (PMID 39202581, 2024). "There were no substantial differences in patient age, infertility years, basal levels of E2 or prolactin (PRL) or days of stimulation between the two groups (p > 0.05)." (PMID 35288625, 2022).